PON1 (paraoxonase 1)
Diseases named in the same sentence as PON1 in open-access papers (continued):
Sharing a sentence is not in itself a finding about the gene and the disease.
hepatocellular carcinoma (20 papers, 2011 to 2025). A malignant tumor that arises from hepatocytes. "PON1 (Q192R and L55M) gene polymorphisms were related to many types of cancer, such as breast, prostate, and hepatocellular carcinoma." (PMID 31467900, 2019). "Resveratrol was shown in several independent studies on hepatocyte cultures and hepatoma cell lines to significantly increase PON1 activity and has been reported to induce PON1 mRNA expression and activity in a human cohort." (PMID 36833509, 2023). "Serum Paraoxonase 1 (PON1) has been reported as a biomarker for evaluating microvascular infiltration in hepatocellular carcinoma." (PMID 36860314, 2023). "Rs854571 and rs854572 map in the promoter region of PON1 gene and have been independently reported to produce an approximatively two-fold change in PON1 expression levels in human hepatoma cell line HepG2." (PMID 27338244, 2016). "In a study which introduced a mixture of IL-6, IL-1, and TNF-α in murine hepatoma cell line Hepa 1–6, a reduction in PON1 mRNA was observed." (PMID 24799979, 2014). "PON1 has emerged as a prognostic biomarker for hepatocellular carcinoma." (PMID 40108724, 2025). "The majority of studies on human cell lines have shown a positive modulation of PON1 activity in response to atorvastatin, and a similar effect was reported for simvastatin and pivastatin, while one study on human hepatoma cells reported a decrease in PON1 activity." (PMID 36833509, 2023). "Some new light on this issue was shed by studies on human hepatocellular carcinoma (HepG2) cell lines treated with methyl parathion and chlorpyriphos, where a significant decrease in PON1 mRNA expression was noted, along with the increased secretion of pro-inflammatory mediators." (PMID 36833509, 2023). "The objective of this study was to explore the association of PON1 rs662 and rs705382 with the risk of chronic hepatitis B (CHB), hepatitis B virus-related liver cirrhosis (LC), and hepatocellular carcinoma (HCC) in patients living in the Guangxi region of southern China." (PMID 26632904, 2015). "The effect of statins on PON1 gene expression was further investigated using a reporter gene assay by measuring luciferase activity of plasmids with a PON1 promoter region transfected into human hepatoma HepG2 cells." (PMID 22548179, 2012). "Notably, resistin down-regulated PON1 expression occurred in hepatocellular carcinoma cultures." (PMID 31390816, 2019). "Thus, paraoxonase 1 might represent an indicator for predicting the survival of patients with hepatocellular carcinoma." (PMID 30477582, 2018). "The liver-specific protein paraoxonase 1 (PON1) was found to be the most relevant indicator of tumor recurrence, invasiveness, and metastasis in the present study, and the downregulation of PON1 might reveal poor survival for patients with hepatocellular carcinoma." (PMID 30477582, 2018). "Anti-inflammatory dexamethasone enhanced PON-1 mRNA level by 2-fold in male and female LPS-treated mice and increased PON-1 expression by 8-fold in Hepa cell, a mouse hepatoma cell line." (PMID 22548179, 2012).
ischemic stroke (20 papers, 2006 to 2024). A stroke disorder caused by obstruction of blood flow to the brain, due to thrombotic (local blood clot formation) or embolic (due to a blood clot or other material traveling from another site) event. "Studies have shown that the genetic variations in PON1 can predict the risk of ischemic stroke and modulate the hydrolyzing effect of PON1 over LDL oxidized phospholipids." (PMID 38474211, 2024). "A study from China found that the rs705381 and rs854571 polymorphisms in the promoter region of PON1 were closely related to the incidence of ischemic stroke in the Han Chinese." (PMID 33628379, 2021). "Low levels of PON1 activity increase ischemic stroke risk, and they are positively associated with HDLc and with unfavorable stroke outcome." (PMID 33153204, 2020). "For instance, SNP rs3735590, located within the site of binding for miR-616 and the 3′-UTR of PON1, has been identified to induce an increase in the levels of expression of PON1 and has been significantly associated with high risk for ischemic stroke." (PMID 33575257, 2020). "Related to lipoprotein components, some polymorphisms of apoB, PAF-AH, and PON1 are also associated with high ischemic stroke risk." (PMID 33153204, 2020). "While there have been fewer studies in ischaemic stroke, there is some evidence of a role for the PON1-192 RR (BB) genotype and also for the PON1 (C-107T) allele in younger ischaemic stroke patients." (PMID 16551349, 2006). "The association between PON1 and ischemic stroke has been investigated in several previous studies." (PMID 29215590, 2017). "Furthermore, there were 2 studies investigating the associations of the PON1 rs705382 polymorphism with ischemic stroke (IS) and sporadic amyotrophic lateral sclerosis (SALS), respectively." (PMID 26632904, 2015). "Paraoxonase 1 gene (PON1) polymorphisms and dietary vegetable and fruit intake are both established determinants of ischemic stroke (IS)." (PMID 29215590, 2017). "Further studies are required to establish a relation between PON1 activity levels and the prognosis of patients with ischemic stroke, and this relationship may have clinical and therapeutic importance in neurological patients." (PMID 38474211, 2024). "As a kind of lipase, in addition to gene polymorphism, the activity of PON1 is also a nonnegligible factor affecting the onset of ischemic stroke." (PMID 33628379, 2021). "Some enzymes associated with LDL and HDL have been proposed as putative ischemic stroke biomarkers, mainly, including platelet-activating factor acetylhydrolases (PAF-AH), also known as lipoprotein-associated phospholipase A2, and paraoxonase-1 (PON1)." (PMID 33153204, 2020). "The purpose of this study was to assess the distribution of polymorphisms of the PON1, PON2 and PON3 genes in well-phenotyped patients with ischaemic stroke and matched control subjects, and to expand on previous studies by examining haplotype distribution in these samples." (PMID 16551349, 2006). "A lower activity of PON-1 has been observed in various autoimmune diseases such as systemic lupus erythematosus, primary and secondary antiphospholipid syndrome, and functional and structural abnormalities of arteries, such as atherosclerotic lesions or ischemic stroke." (PMID 30314292, 2018). "We have analyzed the protein-protein interaction of common targets of FIB and ischemic strokes through STRING database, hidden 2 connectionless nodes (PON1, SCN5A) which involved a total of 31 nodes and 78 edges." (PMID 36467049, 2022). "During the acute stage of ischemic stroke, levels of HDL-related proteins such as alpha-1 anti-trypsin, myeloperoxidase, and paraoxonase-1 may compromise the antioxidant capabilities of HDL." (PMID 39210350, 2024).
lung carcinoma (20 papers, 2014 to 2026). "The expression and activity of PON1 have been associated with lung cancer, multiple myeloma, and papillary thyroid cancer." (PMID 35453382, 2022). "At present, only three studies have been conducted to examine the effect of the PON1 genetic polymorphism on lung cancer risk." (PMID 25741997, 2015). "Nevertheless, our results showed a clear difference in the magnitude of lung cancer risk across PON1 rs662 genotypes according to the smoking status." (PMID 25741997, 2015). "The PON1 rs662 AA genotype showed a significantly lower risk of lung cancer than the GG genotype (OR = 0.60, 95% CI: 0.36–0.99)." (PMID 25741997, 2015). "The effect of the PON1 rs662 polymorphism on the risk of lung cancer differed according to the smoking status." (PMID 25741997, 2015). "In this study, the PON1 192Q allele was associated with lower oxidative stress in non-smoking lung cancer patients, and with an overall reduction in lung cancer risk." (PMID 25741997, 2015). "Among them, the two most recent studies suggested that the 192Q allele of the PON1 is a potential protective factor against lung cancer, which is in concordance with this present study." (PMID 25741997, 2015). "Until now, several epidemiological studies have reported that the PON1 genetic polymorphism is associated with lung cancer risk or reduction of lung function." (PMID 25741997, 2015). "The results of this study indicate that the individuals with one or two rs662 A (192Q) alleles of the PON1 rs662 polymorphism showed a reduced risk for lung cancer." (PMID 25741997, 2015). "PON1 rs662 SNP was marginally associated with lung cancer risk solely in the adenocarcinoma group, which was more common in non-smokers." (PMID 25741997, 2015). "Associations between seven genetic polymorphisms of PON1 and the risk of lung cancer, according to smoking status." (PMID 25741997, 2015). "In addition, we tested the influence of the PON1 SNPs on lung cancer risk after stratification according to histological type." (PMID 25741997, 2015). "In conclusion, the results of this study suggest that functional polymorphisms of PON1 may be associated with the risk of lung cancer and that the effect of PON1 polymorphisms on lung carcinogenesis and oxidative stress may be modulated by tobacco smoking." (PMID 25741997, 2015). "Associations between seven genetic polymorphisms of PON1 and the risk of lung cancer." (PMID 25741997, 2015). "Furthermore, a similar association was also observed between the PON1 rs662 polymorphism and oxidative stress level in lung cancer patients." (PMID 25741997, 2015). "However, in our stratified analyses according to the histological types, differing associations were observed between PON1 rs662 SNP and lung cancer risk for different histological types, although statistical significance was not reached, probably owing to the small sample size." (PMID 25741997, 2015). "Therefore, our present findings suggest that the PON1 192Q allele might reduce lung cancer risk or oxidative stress through increased PON1-arylesterase activity." (PMID 25741997, 2015). "PON1 is a serum esterase with antioxidant and anti‐inflammatory functions, which induces the metastasis of lung cancer cells through its antioxidant activity." (PMID 41523581, 2026). "In cancer studies, PON1 overexpression was recently reported to support the metastatic progression of lung cancer by decreasing the G1/S ratio." (PMID 34679639, 2021). "In lung cancer, as well as head and neck cancer patients treated with RT, PON1 concentration also increased after RT." (PMID 33425072, 2020). "It was reported that expression or activity of PON1 decreased in lung cancer, multiple myeloma and papillary thyroid cancer." (PMID 29254148, 2017).
lung carcinoma (continued). "Here, we interrogated the role of PON1 in the pathobiology of lung cancer (LC) by addressing cell-autonomous mechanisms using gain-of-function and loss-of-function approaches and protein expression profiling of tissue samples in our clinical biobank." (PMID 28467805, 2017). "We investigated the effects of the genetic polymorphisms of paraoxonase 1 (PON1), smoking, and the interaction between the two on lung cancer risk and oxidative stress." (PMID 25741997, 2015). "We found a significant interaction effect between PON1 rs662 SNP and smoking status on the urinary 8-OHdG level in lung cancer patients (Pinteraction = 0.025)." (PMID 25741997, 2015). "Fucosylated alpha-1-acid glycoprotein (AGP), ceruloplasmin (CP), and paraoxonase 1 (PON1) in the serum may be potential biomarkers for lung cancer." (PMID 37256139, 2023). "Thus, all together these data suggest that PON1 antioxidant activity can be maintained through peroxidase-type mechanism in mitochondria regulating ROS in lung cancer cells." (PMID 28467805, 2017). "Furthermore, we observed a significant interaction between the PON1 rs662 SNP and smoking on oxidative stress in lung cancer patients." (PMID 25741997, 2015). "Furthermore, we found a significant interaction effect between PON1 rs662 and smoking status on urinary 8-OHdG levels in lung cancer patients." (PMID 25741997, 2015). "Concordantly, our findings showed that the PON1 rs662 SNP was associated with a significant reduction in the lung cancer risk of non-smokers." (PMID 25741997, 2015). "This case-control study found that the PON1 rs662 (R192Q) polymorphism is associated with a risk of lung cancer, especially among non-smokers." (PMID 25741997, 2015). "This supports our data which indicate that the PON1 rs662 polymorphism was significantly associated with lung cancer risk in non-smokers, but not in ex- or current smokers." (PMID 25741997, 2015). "However, the interaction between the PON1 rs662 polymorphism and smoking habits on lung cancer risk was not statistically significant, probably owing to the relatively small sample size." (PMID 25741997, 2015). "The protective effect of the PON1 rs662 AA genotype on lung cancer risk was limited to non-smokers." (PMID 25741997, 2015). "These facts suggest that PON1 rs662 SNP may be considered as a genetic susceptibility marker for lung cancer in non-smokers." (PMID 25741997, 2015). "We investigated alterations in the levels of the antioxidant paraoxonase-1 (PON1) and the lipoprotein profile (analyzed by nuclear magnetic resonance) in patients with lung cancer (LC) or head and neck cancer (HNC), and the effects produced thereon by radiotherapy (RT)." (PMID 31295833, 2019). "We cannot rule out the possibility that lung cancer can change the action of the PON1 192Q enzyme on oxidative stress." (PMID 25741997, 2015). "Previous studies reported that distributions of SNPs and serum PON1 activity were not different between histological types of lung cancer." (PMID 25741997, 2015). "Our study found that non-smoker lung cancer patients with the PON1 192RR genotype showed a significantly higher level of urinary 8-OHdG than those with the 192RQ and QQ genotypes." (PMID 25741997, 2015). "The protective effect of the PON1 rs662 SNP on 8-OHdG which could be modified by smoking habits was statistically significant only in lung cancer patients, but not in controls." (PMID 25741997, 2015). "However, it is not certain that the protective effect of the PON1 rs662 SNP against oxidative stress exists in the body of lung cancer patients before the start of carcinogenesis." (PMID 25741997, 2015).
Hyperglycemia (18 papers, 2009 to 2026). An increased concentration of glucose in the blood. "In perspectives, PON1 glycation is a novel risk factor of hyperglycemia-induced endothelial dysfunction." (PMID 28374834, 2017). "In all subjects combined, age- and sex-adjusted multivariable linear regression analysis demonstrated that impaired HDL anti-inflammatory capacity was associated with hyperglycemia (β = 0.499, P < 0.001), lower PON-1 activity (β = − 0.192, P = 0.030) and higher hs-CRP (β = 0.220, P = 0.016)." (PMID 29025405, 2017). "However, hyperglycemia and excessive oxidant molecules may cause glycosylation and oxidative damage to PON1, reducing enzyme activity." (PMID 37885002, 2023). "Under conditions of hyperglycemia and oxidative stress, depletion of apoA-I and PON1, reduction in PON1 activity, and enrichment of oxidized fatty acids in HDL all lead to an impairment of the anti-oxidative capacity of HDL." (PMID 38994965, 2024). "In conclusion, glycation of PON1 by hyperglycemia induces endothelial dysfunction through ER stress." (PMID 28374834, 2017). "The HDL anti-inflammatory capacity is substantially impaired in T2DM, at least partly attributable to the degree of hyperglycemia, decreased PON-1 activity and enhanced low grade chronic inflammation." (PMID 29025405, 2017). "Hyperglycemia was associated with significantly lower HDL-C levels and PON1 activity (p<0.05) and significantly higher TG and NEFA levels in the respective CAD patients sera (p<0.01)." (PMID 27519051, 2016). "It is known that in a scenario of hyperglycemia, a decrease in PON-1 activity may be related to the occurrence of the glycation of this enzyme, which may explain, at least in part, the low PON-1 activity in the plasma of the mice from the H and V groups." (PMID 39338363, 2024). "As shown in this study, the decrease in serum PON1 and ARE activities in diabetic rats may be associated with hyperglycemia, hyperlipidemia, and/or oxidative stress." (PMID 33293988, 2020). "In βTC3 cells, PON1 induces insulin secretion and ameliorates cell survival, under hyperglycemia." (PMID 31430977, 2019). "Therefore, in both types of DM, serum PON1 activity and concentration are significantly decreased, since hyperglycemia, oxidative stress, and IR coexist." (PMID 31430977, 2019). "Importantly, administrations of AG reversed these abnormalities in STZ-induced hyperglycemic rats, indicating that hyperglycemia-induced endothelial dysfunction is related to PON1 glycation." (PMID 28374834, 2017). "Furthermore, we aimed to delineate the relationship of this metric of HDL function with hyperglycemia, PON-1 activity and low grade chronic inflammation markers." (PMID 29025405, 2017). "In addition, excessive levels of oxidant molecules and hyperglycemia may lead to oxidative damage and glycosylation of PON1, thereby reducing the enzyme activity." (PMID 41607469, 2026). "A therapeutic intervention able to control hyperglycemia and which increases both HDL and the levels of paraoxonase 1 (PON1) could offer additional protection against long-term diabetic complications." (PMID 28333071, 2017). "Thus, it is likely that hyperglycemia contributes, but not the solo determinant factor, to the impaired functional activities of PON1 in diabetic patients." (PMID 30979955, 2019). "Consequently, they had significantly lower levels of TC, LDL-C, HDL-C, and PON1 activity, and higher TG and apoE levels, regardless of the presence of hyperglycemia." (PMID 27519051, 2016). "Therefore, in addition to mild basal hyperglycemia, 10-week-old adult GK rats also exhibited hyperlipidemia, blood OS (as reflected by oxidized RBC glutathione redox state), but had already mounted blood antioxidant defense (high α-tocopherol level and PON-1 activity)." (PMID 19742300, 2009).